KLF4 (KLF transcription factor 4)
Diseases named in the same sentence as KLF4 in open-access papers (continued):
Sharing a sentence is not in itself a finding about the gene and the disease.
pulmonary hypertension (14 papers, 2017 to 2025). Increased pressure within the pulmonary circulation due to lung or heart disorder. "In parallel, emerging evidence indicates that SIRT7 overexpression attenuates endothelial cell inflammatory responses by regulating KLF4 deacetylation and ameliorates pulmonary hypertension." (PMID 40884727, 2025). "Previous studies identified a new regulatory model of the miR-182-3p/MYADM/KLF4/p21 axis in pulmonary hypertension vascular remodeling." (PMID 39247591, 2024). "Recently, miR-182-3p/Myadm contribute to pulmonary artery hypertension vascular remodeling via a KLF4/p21-dependent mechanism." (PMID 34917199, 2021). "In another disease model of pathological vascular remodeling, KLF4 levels are decreased in the lungs of patients with pulmonary artery hypertension (PAH)." (PMID 29459900, 2018). "Moreover, in pulmonary arterial endothelium cells, the overexpression of SIRT7 reversed EC dysfunction occurring under pulmonary hypertension by deacetylating and stabilizing KLF4." (PMID 38791128, 2024). "Smoking has been shown to increase Kruppel-like factor 4 (KLF4) expression in the airway epithelium and in pulmonary vessels, contributing to their remodeling and the development of pulmonary hypertension by stimulating the proliferation of vascular smooth muscle cells." (PMID 37240069, 2023). "Here, we aim to investigate whether CS‐induced pulmonary hypertension (PH) is prevented and ameliorated by targeted pulmonary vascular gene knockdown of KLF4 via adeno‐associated virus 1 (AAV1)‐KLF4‐shRNA in vivo in rat model." (PMID 33342082, 2021). "We found previously that KLF4 expression was up‐regulated in cultured rat and human pulmonary artery smooth muscle cells (PASMCs) exposed to cigarette smoke (CS) extract and in pulmonary artery from rats with pulmonary hypertension induced by CS." (PMID 33342082, 2021). "Researchers have shown that hypoxia induces high expression of KLF4 in different cells, such as human aortic smooth muscle cells and pulmonary arteriole smooth muscle cells, in mice with hypoxia‐induced pulmonary hypertension and pulmonary hypertension patients." (PMID 38774964, 2024). "However, most of the current studies showed an important role of KLF4 in pulmonary hypertension, while it is not clear whether KLF4 in VSMCs is associated with essential hypertension." (PMID 36312252, 2022).
Sepsis (13 papers, 2019 to 2024). Sepsis is defined as life-threatening organ dysfunction caused by a dysregulated host response to infection. "Our results suggested the potential cascade of rno-miR-146b-5p, Klf4, and Ccnd2 in regulating the pathogenic processes underlying sepsis-induced intestinal injury." (PMID 33200654, 2020). "More relevant to infection, KLF4 downregulation is reported in a mouse model of sepsis, which is consistent with the epigenetic evidence based on our data, whereby the acute LPS-stimulated enhancer is remarkably suppressed upon LPS tolerance, a hallmark of sepsis." (PMID 35751107, 2022). "Krüppel-like factor 4 (KLF4) is a pivotal anti-inflammatory transcription factor that is reportedly involved in the immune response to sepsis." (PMID 39234245, 2024). "Collectively, these results explain the down‐regulation of KLF4 in sepsis, namely via TLR4 promotion of ERK1/2 phosphorylation, and identify ITGA2B as the downstream gene of KLF4, thus highlighting the anti‐inflammatory role of KLF4 in sepsis." (PMID 33369167, 2021). "Taken together, KLF4 was expressed at a low level in mice with sepsis, but elevating KLF4 expression brought considerable alleviation of sepsis." (PMID 33369167, 2021). "In the present study, Klf4 was downregulated in the jejunal tissues of rats with sepsis, and decreased Klf4 expression inhibited the proliferation and promoted the apoptosis of intestinal crypt cells." (PMID 33200654, 2020). "We also measured mRNA levels of Neurod1 and Klf4, which were downregulated in the sepsis group, and levels of Tlr2, which were upregulated in the sepsis group." (PMID 33200654, 2020). "Upon exposure to lipopolysaccharide (LPS), RAW264.7 cells show a suppression of KLF4 expression along with enhanced release of pro‐inflammatory cytokines, implying that KLF4 may be engaged in the immune response in sepsis." (PMID 33369167, 2021). "Accordingly, ITGA2B merits study as the downstream of KLF4 in sepsis." (PMID 33369167, 2021). "The mouse model of sepsis was established to explore the functional role of KLF4." (PMID 33369167, 2021). "During the current investigation, we aimed to prove the hypothesis that the TLR4/ERK1/2/KLF4/ITGA2B axis is capable of mediating inflammatory response of sepsis." (PMID 33369167, 2021). "Herein, we investigate the hypothesis that the TLR4/ERK1/2/KLF4/ITGA2B axis mediates the inflammatory response of sepsis." (PMID 33369167, 2021). "ITGA2B was up‐regulated in the setting of sepsis and was inhibited by KLF4 overexpression." (PMID 33369167, 2021). "Accordingly, we investigated further the role of the TLR4/ERK1/2/KLF4/ITGA2B axis in sepsis." (PMID 33369167, 2021). "To test this hypothesis, we established CLP‐induced septic mice and LPS‐induced RAW264.7 cells and characterized the role of the TLR4/ERK1/2/KLF4/ITGA2B axis in the setting of sepsis in vivo and in vitro." (PMID 33369167, 2021). "Further research on the miR-34a expression and the downstream Klf4 might provide a wider approach and method for the diagnosis and the treatment of ALI caused by sepsis and lung injury." (PMID 32825525, 2020). "Our data indicate that rno-miR-146b-5p and Kruppel-like factor 4 (Klf4) may play an important role in intestinal injury in sepsis." (PMID 33200654, 2020). "rno-miR-146b-5p may play a vital role in the development of sepsis intestinal injury through targeting Klf4 expression and affecting promoter activity of Ccnd2." (PMID 33200654, 2020). "As miRNA typically inhibits the expression of its target genes, we hypothesized that rno-miR-146b-5p inhibits Klf4 in the development of sepsis." (PMID 33200654, 2020). "Rno-miR-146b-5p may be involved in the development sepsis by targeting and regulating the expression of Klf4." (PMID 33200654, 2020). "To conclude, sepsis in mice could be alleviated by KLF4 through down‐regulation of ITGA2B." (PMID 33369167, 2021).
Sepsis (continued). "Exosomes might also contribute to chronic liver dysfunction after sepsis, as exosomal miR-103-3p from LPS-activated macrophages targeted Krüppel-like factor 4 (KLF4) to increase α-SMA, TGF-β, and Col1a1 of hepatic stellate cells, which can contribute to liver fibrosis." (PMID 33013905, 2020). "Thus, we suspect that the upregulation of rno-miR-146b-5p in the sepsis model may inhibit the promoter activity of Ccnd2 owing to reduced Klf4 expression." (PMID 33200654, 2020). "Complement and/or CD14 inhibition successfully reduced the IFN-γ production in mice and baboons’ sepsis studies, thus preventing STAT1 and KLF4 overactivation." (PMID 36059503, 2022). "We found that rno-miR-146b-5p and Klf4 were enriched in the PI3K-Akt signaling pathway, and rno-miR-146b-5p was upregulated in the sepsis rat model." (PMID 33200654, 2020). "Exosomal miR-103-3p from LPS-activated macrophages targets Krüppel-like factor 4 (KLF4), increasing the expression of α-SMA, TGF-β, and Col1a1 in hepatic stellate cells, contributing to chronic liver dysfunction or liver fibrosis post-sepsis." (PMID 38732114, 2024). "KLF4 down‐regulation resulting from promotion by TLR4 of ERK1/2 phosphorylation leads to elevated ITGA2B expression, which underpins the inflammatory response in sepsis." (PMID 33369167, 2021). "In this study, miR-146a-5p–mediated reduction in expressions of Kruppel-like factor 4 (Klf4) and cyclin D2 were thought to inhibit IEC proliferation and worsen gut injury on sepsis, although the role of the septic IEC exosome-derived miR-146b-5p remains unknown." (PMID 35647030, 2022).
Insulin resistance (12 papers, 2014 to 2025). Increased resistance towards insulin, that is, diminished effectiveness of insulin in reducing blood glucose levels. "Gain- and loss-of-function studies indicate that insulin resistance or hyperglycemia-induced downregulation of IRS1 elevates KLF4 expression, a transcriptional repressor of the smooth muscle contractile phenotype." (PMID 40940776, 2025). "When applying BAKE to an experimental animal model of insulin resistance progression, we discovered a novel regulatory transcription factor KLF4 to interact with IRS2 and TSC2, two key intermediates in the insulin signaling pathway." (PMID 30240435, 2018). "Applying BAKE to genomic expression data collected from mouse (Mus musculus) adipocytes during insulin resistance progression, we uncovered the transcription factor Krueppel-like Factor 4 (KLF4) as a regulator of early insulin signaling." (PMID 30240435, 2018). "In addition, potential side effects of repressed KLF4 should not be overlooked, as KLF4 inhibition has been shown to delay wound healing and elevate insulin resistance." (PMID 34470477, 2021). "These investigations suggest that reduced expression of KLF4 triggered by a high-fat diet in our mouse model (IR+/-IRS1+/-ApoE-/-) may mediate down-regulation of IRS2 and TSC2 expression thereby impairing insulin signaling in adipocytes and promoting insulin resistance." (PMID 30240435, 2018).
liver fibrosis (12 papers, 2017 to 2024). "Hyperplasia of hepatocytes is one of the main causes of liver fibrosis, which is consistent with our observations that the expression level of cyclin D1 is apparently lower in CCl4-treated KLF4-overexpressing mice than in those pretreated with the null plasmid." (PMID 31687083, 2019). "Combined with our observations, CHOP may promote liver fibrosis caused by S. japonicum by reducing the expression of KLF4 and activating M2 macrophages." (PMID 31886304, 2019). "Additionally, paraplastic hepatocytes are one of the main causes of liver fibrosis, and RT-PCR and Western blotting analyses showed that cyclin D1 expression levels were apparently lower in the KLF4-overexpressing mice than in those treated with the null plasmid prior to CCl4 administration." (PMID 31687083, 2019). "The conclusive evidence from these studies clearly highlighted that certain members of the SP/KLF family (SP1, KLF6, and KLF4) promote the transcriptional regulation of fibrotic remodeling, facilitating the incidence and progression of liver fibrosis." (PMID 36902112, 2023). "Our study found that KLF4 reduction is involved in the process of liver fibrosis induced by S. japonicum." (PMID 31886304, 2019). "At the same time, studies have found that KLF4 expression is decreased in patients with liver fibrosis and rat liver, and the results show that decreased expression of KLF4 can activate HSCs." (PMID 31886304, 2019). "In the early stage of liver fibrosis, the expression of KLF4 is higher to maintain the stability of activated HSCs and inhibit the differentiation and activation of HSCs." (PMID 31886304, 2019). "Consistent with this, in the liver fibrosis model, KLF4 expression was decreased in hepatic stellate cells." (PMID 31886304, 2019). "It was also found that KLF5 promoted collagen deposition in the hepatic stellate cells of liver fibrosis rat models, whereas KLF4 inhibited the synthesis of collagen in human hepatic stellate cells." (PMID 31829402, 2019). "Similarly, KLF4 is pro-fibrotic, as shown with reduced hepatic fibrosis following treatment with siRNA against KLF4." (PMID 36902112, 2023). "In C57BL/6 mice, iron overload induced decreased KLF4 expression and liver fibrosis." (PMID 31886304, 2019). "In summary, we speculate that KLF4 may play different roles in different disease models or organs, and KLF4 expression in different cell types may have different effects on the formation of liver fibrosis." (PMID 31886304, 2019). "With the progression of liver fibrosis, the expression of KLF4 is gradually inhibited." (PMID 31886304, 2019). "Moreover, there was a compensatory increase in KLF4 expression upon KLF2 knockdown which suggested a potential role of KLF4 in pathogenesis of liver fibrosis." (PMID 28091538, 2017). "miR-145 promotes HSC activation and liver fibrosis by targeting KLF4." (PMID 28091538, 2017). "However, the potential role of KLF4 and miR-145 in hepatic stellate cells (HSCs) activation or in hepatic fibrosis keeps unclear." (PMID 28091538, 2017). "We considered whether KLF4 is involved in the model of S. japonicum liver fibrosis." (PMID 31886304, 2019). "Moreover, we determined the role of KLF4 in HSCs activation and liver fibrosis." (PMID 28091538, 2017). "Among them, miR-146b can target Krüppel-like factor 4 (KLF4) to activate HSC, and hepatocyte nuclear factor 1A (HNF1A) to downregulate its expression, enhancing liver fibrosis." (PMID 39008169, 2024). "miR-103-3p activation in exosomes promotes HSC activation and proliferation by targeting Kruppel-like factor 4 (KLF4) and plays an important role in the crosstalk between THP-1 macrophages and HSCs during the progression of liver fibrosis." (PMID 34064375, 2021). "Studies have confirmed that KLF4 can regulate pathological processes such as liver fibrosis and HCC formation, and a recent study reported that KLF4 promoted HepG2 cell scattering induced by hepatocyte growth factor." (PMID 31687083, 2019).
liver fibrosis (continued). "KLF4 knockdown induced α-SMA and COL-I expression, while overexpressing KLF4 suppressed α-SMA and COL-I expression in HSCs, demonstrated that KLF4 is a key inhibitory factor for liver fibrosis." (PMID 28091538, 2017). "Given the effect of KLF4 on α-SMA transcription, the role of KLF4 in activation of HSCs and in hepatic fibrosis/cirrhosis remains to be determined." (PMID 28091538, 2017).
nasopharyngeal carcinoma (12 papers, 2014 to 2024). A carcinoma arising from the nasopharyngeal epithelium. "Other reports suggest an adverse function of KLF4, as loss of cytoplasmic or nuclear expression of KLF4 was related to a poor prognosis in nasopharyngeal carcinoma and oral cancer." (PMID 35629138, 2022). "PLK1 phosphorylates KLF4 and recruits TRAF6, which leads to K63-linked ubiquitination of KLF4 at K32 site and promotes nasopharyngeal cancer." (PMID 36202787, 2022). "The expression of Klf4 in the nucleus was associated with prognosis in 168 patients with cetuximab-treated nasopharyngeal carcinoma, which was found by retrospective analysis." (PMID 29973197, 2018). "Given the fact that lots of conflicting result were reported, it is important to clarify the accurate expression and underlying molecular mechanism of KLF4 in nasopharyngeal carcinoma." (PMID 30108202, 2018). "Furthermore, of the 168 cases of nasopharyngeal carcinoma patients, 56 showed a high expression of KLF4 in the nucleus that can cause poor prognosis of nasopharyngeal carcinoma (P = 0.011)." (PMID 29973197, 2018). "The expression of Klf4 in the nucleus can be used as a biomarker for predicting the effects of cetuximab treatment in nasopharyngeal carcinoma, which might be attributed to the H-RAS and PI3K mutations, leading to cetuximab resistance." (PMID 29973197, 2018). "We expect that the results of the present study may shed light into a novel mechanism underlying the function of transcription factor SOX2 and KLF4 in nasopharyngeal carcinoma, and provide a rationale for its early detection and effective therapeutic strategies." (PMID 30108202, 2018). "KLF4 can also inhibit nasopharyngeal carcinoma stem cells, reverse epithelial-mesenchymal transition, and block the progression of nasopharyngeal carcinoma." (PMID 39695175, 2024). "miRNA-296-5p enhances the drug sensitivity of nasopharyngeal carcinoma cells to cisplatin via STAT3/KLF4 signaling pathway." (PMID 38509141, 2024). "The expression of Klf4 in the nucleus was correlated with mutations of H-Ras and PI3K in 168 cases of nasopharyngeal carcinoma with cetuximab treatment." (PMID 29973197, 2018). "Presently, several studies showed that the expressions of Ras and PI3K were related to KLF4, and our study showed that the mutations in H-Ras and PI3K were associated with KLF4 in nasopharyngeal carcinoma." (PMID 29973197, 2018). "In our study, we confirmed that KLF4 exhibited remarkably overexpression both in clinical nasopharyngeal carcinoma specimens and sequencing data from TCGA database." (PMID 30108202, 2018). "In the nasopharyngeal carcinoma with H-Ras and PI3K mutations, the level of nuclear KLF4 was increased, and the difference was statistically significant (P < 0.05)." (PMID 29973197, 2018). "We also demonstrated that knockdown of KLF4 significantly inhibited tumor growth, which further confirmed that KLF4 served as an oncogene in nasopharyngeal carcinoma." (PMID 30108202, 2018). "Previously, KLF4 was found to be expressed in the cytoplasm of nasopharyngeal carcinoma, and it played a role as tumor suppressor gene." (PMID 29973197, 2018). "KLF4 was found to specifically express in the cytoplasm by deleting the NES, while H-Ras and PI3K genes were mutated in the nasopharyngeal carcinoma 5–8F and HONE1cell line." (PMID 29973197, 2018). "In conclusion, our results revealed that aberrant nuclear Klf4 expression can lead to cetuximab drug-resistance of nasopharyngeal carcinoma patients." (PMID 29973197, 2018). "By consistently knocking down expression of KLF4 in HNE-1 and C666-1 cell lines, we demonstrated that depletion of KLF4 significantly inhibited nasopharyngeal carcinoma growth both in vitro and in vivo." (PMID 30108202, 2018). "Similarly, in nasopharyngeal carcinoma, KLF4 can transcriptionally activate E-cadherin and reduce the motility and invasion of cells." (PMID 34680284, 2021). "The role of KLF4 in nasopharyngeal carcinoma attracted increasing attention." (PMID 29973197, 2018).